KRAS (KRas proto-oncogene, GTPase)
Diseases named in the same sentence as KRAS in open-access papers (continued):
Sharing a sentence is not in itself a finding about the gene and the disease.
colon carcinoma (continued). "Therefore, the aim of this study was to investigate the association of low-dose aspirin use after colon cancer diagnosis and survival of patients according to BRAF and KRAS mutation status." (PMID 28125730, 2017). "This study found that BRAF mutation status and KRAS mutation status were not distinctive in the association between low-dose aspirin use and a survival benefit in patients with colon cancer." (PMID 28125730, 2017). "The difference in responses among these wild‐type KRAS colon cancer models may provide an intriguing tool for exploring determinants or predictive markers of the response." (PMID 28486761, 2017). "Blockade of extracellular WSTF could restore cetuximab sensitivity of colon cancer cells with mutant KRAS." (PMID 27449290, 2016). "Oncogenic pathways, including KRAS/BRAF that occur in high frequency in colon cancer, circumvent the canonical HH-GLI axis by converging on and further driving GLI to a higher activating state in tumor cells, promoting cellular proliferation, tumor progression and survival." (PMID 27863397, 2016). "Considering that the presence of mutations in KRAS gene renders tumor cells inherently resistant to anti-EGFR therapy, our results indicate that miR-143 or miR-145 may be key players in mitigating cetuximab resistance in mutant KRAS colon cancer cells." (PMID 26824186, 2016). "In addition, forced expression of these miRNAs in both mutant and wild-type KRAS colon cancer cells increased their sensitivity to cetuximab by increasing cetuximab-mediated ADCC." (PMID 26824186, 2016). "Importantly, compared with KRAS-mutated TSA, BRAF-mutated TSA is significantly associated with a proximal colonic tumor location and more widespread CpG island methylation." (PMID 26883113, 2016). "We have previously shown that the HSP90 inhibitor AUY922 kills colon cancer cells through apoptosis and that wild-type KRAS colon cancer cells are more resistant to apoptosis induced by AUY922 compared with those carrying active mutations in KRAS." (PMID 27391062, 2016). "We next explored the relationship between XPi2 and the KRAS gene in colon cancer patients." (PMID 27880931, 2016). "Indeed, a number of HSP90 inhibitors such as AUY922 that do not significantly affect normal cell survival are currently in clinical studies for the treatment of various types of cancers including wild-type KRAS colon cancer." (PMID 27391062, 2016). "Considering rare data provided for NRAS mutations in stage II/III colon cancer, large population cohort investigation for this gene mutation detection should be performed, as NRAS closely related to KRAS and NRAS mutation was prognostic for EGFR MoAbs therapy inmCRC28." (PMID 27074743, 2016). "Therefore, we propose that restoration of these miRNAs contributes to cetuximab sensitization both in KRAS mutant cetuximab-resistant and in KRAS wild-type colon cancer cells." (PMID 26824186, 2016). "At concentrations <5 μM IQcs 2d, 3d and 3e inhibited KRAS promoter activity by up to 50% in the luciferase dual-reporter assay and inhibited mutated KRAS expression at both mRNA and protein levels in the HCT116 and metastatic SW620 colon cancer cell lines." (PMID 25853628, 2015). "Colon cancer cells with and without oncogenic mutations such as KRAS and BRAF mutations were treated with erlotinib, an inhibitor of epidermal growth factor receptor, in order to detect the impact of these mutations on Raman spectra of the cells." (PMID 26168967, 2015). "The results show that IQcs significantly reduced KRAS transcription in colon cancer cells." (PMID 25853628, 2015).
colon carcinoma (continued). "They preferentially inhibit the proliferation of KRAS mutant cancer cell lines (0.22 < IC50 < 4.80 μM), down-regulate KRAS promoter activity in a luciferase reporter assay, and reduce both KRAS mRNA and p21KRAS steady-state levels in mutant KRAS colon cancer cell lines." (PMID 25853628, 2015). "The role of BRAF V600E and KRAS mutations in the classification of early stage colon cancer is not well-defined." (PMID 25956750, 2015). "Anti-EGFR antibody, cetuximab or panitumumab is a treatment for colon cancer that is highly effective to patients with expression of EGFR protein; however, it has been reported that patients with KRAS gene mutations that lie downstream acquire resistance against therapy." (PMID 25936694, 2015). "We have established a state-of-theart measurement system using QProbe (QP) method that allows simultaneous measurement of KRAS codon 12/13, p.G13D and BRAF mutation, and compared this method against Direct Sequencing (DS) using 182 specimens from colon cancer patients." (PMID 25936694, 2015). "Verification of tumor cell identity for single cells isolated by DEPArray from spiking experiments using the SW480 colon carcinoma cell line and the MCF-7 breast cancer cell line was achieved by sequencing of the known KRAS (G12V) and PIK3CA (E545K) mutations, respectively." (PMID 25133137, 2014). "Luo and colleagues transfected 74,905 shRNAs targeting 32,293 transcripts in colon cancer cell lines with or without KRAS mutation (Ras Mut and Ras WT)." (PMID 24955791, 2014). "Reovirus preferentially induces apoptosis in KRAS mutant colon cancer cells." (PMID 24798549, 2014). "Of the 34 samples from the colon cancer patients, real-time Bi-PAP detected 14 KRAS mutant samples whereas the traditional real-time allele-specific PCR missed two samples with mutation abundance <1% and DNA sequencing missed nine samples with mutation abundance <10%." (PMID 24769870, 2014). "In CRC, oncogenic KRAS is required to maintain changes in cytoskeletal organization, adhesion, and motility of colon cancer cells; however, differential effects of oncogenic KRAS and N-RAS have been reported on proliferation, differentiation and tumor progression in the colon." (PMID 25361007, 2014). "Since colon cancer cell lines used in this study harbored either different KRAS or BRAF mutation, our results suggest that B4GALNT3 knockdown suppressed cell malignant phenotype and cancer cell stemness irrelevantly to the status of KRAS and BRAF." (PMID 25003232, 2014). "The presence of HER2 overexpression in KRAS mutant colon cancer was found in 5.3%." (PMID 24668895, 2014). "Regarding the primary location, 64.8% of KRAS mutations (p=0.07) and 58% of PIK3CA mutations (p=0.036) occurred in left-sided colorectal tumours, whereas four (66.7%) of BRAF mutations in right-sided colon carcinomas (p=0.024)." (PMID 23374602, 2013). "We therefore designed the small molecule Cdc42 inhibitor AZA197 and show that inhibition of Cdc42 activity with AZA197 acts to reduce tumor growth and significantly improve animal survival in SW620 cells which are a model of KRAS mutant colon cancer xenografts." (PMID 24279335, 2013). "Together, these data identify 5-FU-resistant colon cancer with wild-type KRAS genes as a suitable clinical setting that may benefit from ISC-4 and cetuximab combinatorial therapy." (PMID 23555026, 2013). "Furthermore, we show that systemic AZA197 treatment in vivo reduces primary tumor growth and prolongs survival in KRAS mutant colon cancer xenograft-bearing mice." (PMID 24279335, 2013). "We propose that therapy targeting Rho GTPase Cdc42 signaling pathways may be effective for treatment of patients with advanced colon cancer overexpressing Cdc42 and particularly those with KRAS-mutant disease." (PMID 24279335, 2013).
colon carcinoma (continued). "KRAS, BRAF and PIK3CA mutations are commonly found in colon cancers." (PMID 23617638, 2013). "Cetuximab and Panitumumab are targeted against wild-type KRAS in colon cancers." (PMID 23863689, 2013). "Previous studies have identified ERK5 and KRAS as miR-143 targets in colon cancer." (PMID 22691140, 2012). "In order to gain further insight into the transcriptional modifications induced by the combined treatments, the expression of a selected panel of genes related to Wnt and KRAS signalling, colon cancer and apoptosis, was studied using a home-made quantitative PCR array." (PMID 23227266, 2012). "There is growing focus on elucidating the role of let-7 miRNA in colon cancer, since it may be a KRAS-driven cancer." (PMID 23202889, 2012). "The targeting effect of miR-18a on KRAS has been demonstrated in colon cancer cell lines irrespective of KRAS mutation status." (PMID 22804917, 2012). "Approximately half of colon cancers express a constitutively active KRAS protein." (PMID 23227266, 2012). "In wild-type KRAS colon cancer, EGFR amplification has also been reported as a predictive marker." (PMID 24212636, 2011). "In contrast, recent analyses from the CALGB89803 (stage III) and PETACC-3 study (stage II and III) trials did not demonstrate KRAS mutation to be a prognostic marker for colon cancer patients treated with adjuvant 5FU-based chemotherapy." (PMID 20959826, 2010). "Moreover, while the high frequency of KRAS, BRAF and PIK3CA mutations in colon cancer is well documented, other potentially important mutations have not been profiled with a large number of clinical samples." (PMID 20233444, 2010). "The patient had 10 years earlier developed two synchronous colon cancers, both of which were retrospectively analyzed, but neither of these contained any KRAS mutation (data not shown)." (PMID 19832985, 2009). "KRAS mutations have been reported by several independent groups to be negatively associated with response to EGFR tyrosine kinase inhibitors in lung cancer and EGFR-directed antibodies in colon cancer." (PMID 19636423, 2009). "However, mutant KRAS significantly affected the expression of a greater number of mRNAs in colon cancer cells and was still more redundant with c-Myc than the other way around, suggesting that the mechanism is more complex than the simple domination of a broader expression regulator." (PMID 39217152, 2024). "Subsequently, an assessment of HALLMARK gene set enrichment in colon cancer tissues revealed a significant positive correlation between PRS and pathways associated with tumor progression such as epithelial-to-mesenchymal-transition, Angiogenesis, and KRAS signaling pathways." (PMID 38577604, 2024). "However, this crosstalk may also restrict p38γ activity to phosphorylate and/or to enhance PTPH1 dephosphorylating oncogenic substrates such as EGFR to confer the phenotype of KRAS-mutant colon cancer resistant to EGFR inhibitors." (PMID 37443708, 2023). "Additionally, tumor molecular markers, such as the microsatellite status, the CpG island methylator phenotype (CIMP) status, driver gene mutations, such as KRAS and BRAF, and tumor immune microenvironment, have been linked to different recurrence risks of stage III colon cancer." (PMID 36593480, 2023). "However, in a retrospective analysis of 345 patients treated for stage I–III colon cancer, of whom 40% were KRAS-mutated, KRAS mutation status was not a significant prognostic factor for disease-free survival or overall survival." (PMID 36836752, 2023).
colon carcinoma (continued). "Therefore, the current results indicate a potential role of the Warburg-effect in the etiological pathway between adiposity and colon cancer in women through KRAS mutations, but not other molecular features." (PMID 35546360, 2022). "Since the expression of KRAS mutations hinder the use of anti-epidermal growth factor receptor (EGFR) treatments, the presence of CTCs harboring KRAS mutations in wild-type colon cancers might explain the therapeutic EGFR inhibition failure, thus being indicative of treatment resistance." (PMID 35582538, 2022). "Colon cancer was a highly heterogeneous disease, resulting from a series of distinct genetic and epigenetic changes, and a subset of molecular alterations was considered to drive the cellular and clinical behavior of cancer, including MSI, CIMP, CIN, BRAF, and KRAS mutations." (PMID 36276973, 2022). "HSP90 inhibition has also been shown to preferentially induce apoptosis in KRAS-mutant colon cancer cells in vitro and in a colon cancer-derived xenograft model in nu/nu mice, indicating that this vulnerability might translate across different RAS-mutant tumor types." (PMID 35147163, 2022). "The KRAS mutant colon cancer cells might be more sensitive to SsI." (PMID 35889255, 2022). "Except for the N stage and KRAS status, the increased CRP-MCV was associated with males; older age (older than 60 years); presenting advanced T stage, M stage, and later TNM stage; accompanied by microsatellite instability; and right-sided and poorly differentiated colon cancer." (PMID 34221966, 2021). "Hence, development of KRAS targeting in colon cancer therapeutics is of essence." (PMID 34781949, 2021). "Indeed, we found KRAS mutation was an independent risk factor for left side colon cancer but not right side colon cancer." (PMID 32547859, 2020). "Since KRAS and BRAF gene mutations are frequently present in colon cancers and have adverse prognostic significance, we examined whether mutations in these genes were more prevalent in tumors with high STAT1 expression, which could have contributed to poor prognosis." (PMID 32275681, 2020). "Additionally, tumor molecular markers, such as microsatellite status, CpG island methylator phenotype (CIMP) status, BRAF mutations, and KRAS mutations as well as tumor immune infiltration have been linked to different recurrence risks and survival outcomes in patients with stage III colon cancer." (PMID 31619288, 2019). "Interestingly, KRAS G12D mice did not develop colon cancer, indicating that the expression of this mutant variant is not sufficient to promote neoplasia." (PMID 31681616, 2019). "Consistently, single drug treatment resulted in fewer formed colonies, and the combination drugs imposed the most severe growth inhibition on the tested cells, suggesting that ABT263 + AXIT in combination may be a potent inhibitor for the growth of KRAS-mutant colon cancer cells (P < 0.001)." (PMID 30674639, 2019).
colon carcinoma (continued). "Based on a cohort of 48 stage I-II colon cancer patients, we set out to characterize consistent expression differences in sRNAs between cancer and normal tissue, and between colon cancer subtypes characterized by MSI status, BRAF and KRAS mutations, and tumor location." (PMID 30786859, 2019). "Notably, patient No. 1 who was diagnosed with right-side colon cancer with a KRAS G13D mutation and sigmoid colon cancer with a KRAS G12V mutation in tumor tissues suffered from synchronous liver metastases." (PMID 31164904, 2019). "While they could detect KRAS-mutated colon carcinoma, all renal tumors were negative by NGS, and only 1 out of 9 samples was positive by mutation assay." (PMID 30116406, 2018). "We compared the cytotoxicity; reactive oxygen species (ROS) and GSH modulations induced by DMF in several human primary tumors, with or without KRAS mutations and confirmed our findings by the genetic modulation of p.G12V KRAS in a Caco-2 colon cancer cell line that is not KRAS mutated." (PMID 29507676, 2018). "Other studies suggested that BRAF mutations confer a poorer prognosis on stage II to III colon cancers, but no conclusive prognostic significance for KRAS mutations could be reached among early and medium stage CRCs16–18." (PMID 29666387, 2018). "In addition, the current study did not consider the KRAS/NRAS/BRAF mutation statuses in colon cancer cells which are important for clinical outcomes and survival in cancer patients." (PMID 29732005, 2018). "The mutation status of KRAS (exons 2, codon 12/13), NRAS (exons 2/3/4, codon 12/13/59/61/117/146) and BRAF (exons 15, codon 600) were detected by amplification refractory mutation system polymerase chain reaction (ARMS-PCR) in 86 colon cancer, 140 rectal cancer and 34 gastric cancer tissues." (PMID 30416987, 2018). "Moreover, it has also been reported an increased KRAS expression in human colon carcinomas." (PMID 28259135, 2017). "In addition, PBR suppressed the cell proliferation of KRAS wild-type colon cancer HT-29 cells." (PMID 28800074, 2017). "In addition, it was reported that decreased miR-143 expression might contribute to the pathogenesis of colon cancer by up-regulating KRAS expression, and miR-143 down-regulation correlates with poor prognosis in wild-type KRAS patients." (PMID 26824186, 2016). "However, whether mutations in KRAS together with downstream factors BRAF, PIK3CA and NRAS impact prognosis is still unclear for stage II-III colon cancer." (PMID 27074743, 2016). "Information about the tumor genotype, and in particular about mutations in PI3K/AKT, KRAS and BRAF are currently used to predict the success of systemic chemotherapy of different types of tumors and are used to stratify patients for treatment options for example in colon cancer." (PMID 26799289, 2016). "Thus, targeting KRAS at the genomic level with G4 ligands may be a new anticancer therapy strategy for colon cancer." (PMID 26024321, 2015). "Herein we provide evidence that G4 ligands such as IQ3A compounds can target G4 motifs present in KRAS promoter, down-regulate the expression of the mutant KRAS gene through inhibition of transcription and translation, and induce cell death by apoptosis in colon cancer cell lines." (PMID 26024321, 2015).